ENSG00000272166
Gene: Small nucleolar RNA gene on chromosome 3 (25,555,543 to 25,555,606, reverse strand). Ensembl gene ENSG00000272166.
Homologues: Paralogues in human: SNORD5 (77% identical).